ATAD3A (ATPase family AAA domain containing 3A)
Description:
Essential for mitochondrial network organization, mitochondrial metabolism and cell growth at organism and cellular level. May play an important role in mitochondrial protein synthesis. May also participate in mitochondrial DNA replication. May bind to mitochondrial DNA D-loops and contribute to nucleoid stability. Required for enhanced channeling of cholesterol for hormone-dependent steroidogenesis. Involved in mitochondrial-mediated antiviral innate immunity. Required to protect mitochondria from the PERK-mediated unfolded protein response: specifically inhibits the activity of EIF2AK3/PERK at mitochondria-endoplasmic reticulum contact sites, thereby providing a safe haven for mitochondrial protein translation during endoplasmic reticulum stress. Ability to inhibit EIF2AK3/PERK is independent of its ATPase activity. Also involved in the mitochondrial DNA damage response by promoting signaling between damaged genomes and the mitochondrial membrane, leading to activation of the integrated stress response (ISR).
Synonyms: FLJ10709; HAYOS; PHRINL
Tractability: Antibody: UniProt predicts a signal peptide or a membrane-spanning region. PROTAC: ubiquitination databases record sites on it; its protein half-life has been measured.
Target class: Enzyme; Hydrolase
Gene: Protein-coding gene on chromosome 1 (1,512,147 to 1,534,686, forward strand). Ensembl gene ENSG00000197785.
Subcellular location: Mitochondrion inner membrane; Mitochondrion matrix, mitochondrion nucleoid
Subcellular location (Human Protein Atlas): Mitochondria; Acrosome
Gene Ontology:
Molecular function: ATP binding; ATP hydrolysis activity; protein binding; protein serine/threonine kinase inhibitor activity
Biological process: antiviral innate immune response; DNA damage response; HRI-mediated signaling; mitochondrion organization; negative regulation of apoptotic process; negative regulation of PERK-mediated unfolded protein response; regulation of cell growth
Cellular component: mitochondria-associated endoplasmic reticulum membrane contact site; mitochondrial inner membrane; mitochondrion; mitochondrial nucleoid
Genetic constraint (gnomAD): Loss-of-function variants: 43 observed, 64.43 expected, observed/expected ratio (o/e) 0.67, 90% interval 0.52 to 0.86. The upper end of that interval is the gene's LOEUF score, 0.86, which puts it in group 3 of 6, group 1 being the genes least tolerant of losing a copy. Missense variants: 697 observed, 751.47 expected, observed/expected ratio (o/e) 0.93, 90% interval 0.87 to 0.99. Synonymous variants: 318 observed, 318.4 expected, observed/expected ratio (o/e) 1, 90% interval 0.91 to 1.1.
Homologues: Orthologues: dog ATAD3A (93% identical), rat Atad3a (92% identical), mouse Atad3a (92% identical), guinea pig ATAD3A (91% identical), tropical clawed frog atad3a (81% identical), pig ATAD3A (78% identical), Drosophila melanogaster bor (63% identical). Paralogues in human: ATAD3B (93% identical), ATAD3C (62% identical).
Diseases named in the same sentence as ATAD3A in open-access papers:
ATAD3A is named in the same sentence as 76 diseases in open-access papers, as found by Europe PMC text mining. Sharing a sentence is not in itself a finding about the gene and the disease. The quoted sentences say what the papers report.
breast carcinoma (10 papers, 2019 to 2024). "Our previous study has demonstrated that loss of ATAD3A suppresses invasion potential in breast cancer cells." (PMID 35093151, 2022). "However, in breast cancer, low expression of ATAD3A was associated with shorter overall survival compared to high expression of ATAD3A." (PMID 37569886, 2023). "Silencing ATAD3A can also inhibit the growth of mammary tumors in mouse breast cancer models, and the tumors generated significantly smaller while ATAD3A knockdown." (PMID 38018291, 2023). "MUC1 degrades ATAD3A by inducing ubiquitination and promotes mitophagy in a Pink1-dependent manner, thereby inducing breast cancer progression." (PMID 36831455, 2023). "We then examined the expression of ATAD3A in 399 breast cancer samples from the multicentric clinical cohort where patients underwent mastectomy and received the standard chemotherapy." (PMID 36627348, 2023). "To determine the function of Atad3a in tumor growth, we used RNA interference to deplete Atad3a in 4T1 murine breast cancer cells." (PMID 36627348, 2023). "ATAD3A increases breast cancer metastasis through metastasis promoter WASF3, and knockdown of ATAD3A can inhibit the migration of colon cancer cells and breast cancer cells." (PMID 38018291, 2023). "Some scholars established the mouse model of ATAD3A knockout breast cancer cells in the process of research and found that the metastasis rate of corresponding breast cancer cells was significantly reduced in the Lung Group." (PMID 38018291, 2023). "Consistently, MUC1 and ATAD3A protein levels present an inverse relationship in tumor tissues of breast cancer patients." (PMID 36289190, 2022). "Reliably, an inverse correlation between MUC1 and ATAD3A was found in tumor tissues of breast cancer patients." (PMID 36289190, 2022). "Using LC-MS/MS analysis, we identified the mitochondrial protein ATAD3A that interacted with MUC1 in breast cancer cells." (PMID 36289190, 2022). "Our results suggested that MUC1/ATAD3A/Pink1 axis-mediated mitophagy improved cancer cell proliferation, mammosphere formation, and tumor growth, suggesting a tumor-promoting role in breast cancers." (PMID 36289190, 2022). "To examine the clinical relevance of MUC1 and ATAD3A in breast cancers, we collected 110 samples from breast cancer patients." (PMID 36289190, 2022). "It appears that E-Cadherin is one of the downstream targets of WASF3 in breast cancer cells and impaired invasion of ATAD3A knockdown cells can be rescued by restoring WASF3 protein function." (PMID 33113782, 2020). "Elevated levels of ATAD3A have been found in lung adenocarcinomas, prostate cancer, head and neck cancer, gliomas, uterine cervical cancer, and breast cancer." (PMID 33113782, 2020). "In particular, overexpression of ATAD3A advances breast cancer metastasis by increasing the stability of WASF3 protein, a well-studied tumor metastasis promoter." (PMID 33113782, 2020). "Previous work from our group has demonstrated that silencing ATAD3A by shRNA inhibits cell anchorage-independent growth of MDA-MB-231 breast cancer cells and SW620 colon cancer cells." (PMID 33113782, 2020). "Our recent study demonstrates that ATAD3A regulates the invasion and metastatic potential of breast cancer cells through interacting with Wiskott–Aldridge syndrome family protein 3 (WASF3)." (PMID 33113782, 2020). "We further assessed the impact of ATAD3A on the oncogenic properties of breast cancer cells." (PMID 36289190, 2022). "The gene expression profiling from microarray analysis showed that the expression levels of E-Cadherin/CDH1, a critical gene in maintaining cell–cell adhesion and epithelial–mesenchymal transition, were significantly upregulated in breast cancer cells when ATAD3A was knocked down." (PMID 33113782, 2020).
breast carcinoma (continued). "MUC1 also enhances the invasiveness of breast cancer cells by disrupting ATAD3A and activating Pink1-related mitochondrial autophagy, revealing the critical role of the MUC1/ATAD3A/Pink1 axis in breast cancer progression." (PMID 38361923, 2024). "ATAD3A is differentially expressed between paclitaxel-resistant and -sensitive MCF7 breast cancer cells." (PMID 33717664, 2021). "ATAD3A is a novel interacting partner of WASF3 and acts as a crucial mediator to promote cell invasion in breast cancer by regulating the stabilization of WASF3 with the ER protein GPR78, a resident chaperone involved in protein degradation." (PMID 33113782, 2020). "Kaplan-Meier analysis revealed that high expression of ATAD3A was significantly associated with shortened PFS and OS of patients with TNBC but not those with other breast cancer subtypes." (PMID 36627348, 2023). "Immunohistochemical (IHC) staining analysis revealed a negative correlation between MUC1 and ATAD3A not only in all breast cancer patients but also in four subtypes of breast cancer patients—luminal A, luminal B, HER2 and TNBC." (PMID 36289190, 2022). "A positive correlation between ATAD3A and cancer metastasis has been identified in several types of cancer, such as prostate cancer, urothelial carcinoma (UCC), lung adenocarcinoma (LADC), and breast cancer." (PMID 33113782, 2020). "In this study, we detected three mitochondrial proteins (CPS1, ATAD3A/ATAD3B, and ABHD11) and one lysosomal protein (cathepsin D) with different expressions in paclitaxel-resistant MCF7/PacR breast cancer cells compared to paclitaxel-sensitive MCF7 breast cancer cells." (PMID 31248089, 2019). "In summary, the present study reports a novel model in which MUC1/ATAD3A/Pink1 axis-mediated mitophagy plays a crucial role in maintaining the malignant properties of cancer cells, providing a novel therapeutic target for the management of MUC1-positive breast cancers." (PMID 36289190, 2022).
hepatocellular carcinoma (8 papers, 2020 to 2023). A malignant tumor that arises from hepatocytes. "Silencing ATAD3A can promote tumorigenesis in a hepatocellular carcinoma xenograft model, whereas high-ATAD3A levels suggest a better prognosis." (PMID 36289190, 2022). "A study has revealed that ATAD3A is upregulated in hepatocellular carcinoma and ATAD3A upregulation is correlated with poor prognosis." (PMID 33717664, 2021). "We found that hypoxia induced sorafenib resistance in hepatoma cells was accompanied by hyperactivated mitophagy and a downregulation of ATAD3A expression." (PMID 33280610, 2020). "We generated a tumor sample tissue array containing 135 hepatocellular carcinoma samples with survival information and 85 cases with paired normal tissues to determine ATAD3A expression by IHC." (PMID 33280610, 2020). "This was confirmed by treating hepatoma cells with CoCl2 and/or the miR-210-5P inhibitor, which showed that hypoxia-induced downregulation of ATAD3A was abrogated by blocking miR-210-5P." (PMID 33280610, 2020). "Hepatoma cells transfected with miR-210-5P mimic significantly inhibited ATAD3A expression, whereas miR-210-5p inhibitor had the opposite effect." (PMID 33280610, 2020). "Hypoxia treatment significantly down regulated ATAD3A expression in hepatoma cells." (PMID 33280610, 2020). "ATAD3A was reported to be upregulated in certain types of cancer, including hepatocellular carcinoma (HCC), head and neck squamous cell carcinoma (HNSCC), and lung adenocarcinoma." (PMID 37569886, 2023). "The association with ATAD3A and ATAD3B expression may be of interest since ATAD3 over-expression has been linked to the progression of head and neck cancer, lung adenocarcinoma, non‐Hodgkin's lymphoma, uterine cancer, cervical cancer, prostate cancer, glioma, and hepatocellular carcinoma." (PMID 35525914, 2022). "For example, suppression of ATPase family AAA domain-containing 3A (ATAD3A) by the upregulation of the microRNA miR-210-5P was shown to induce mitochondrial autophagy and sorafenib resistance in hepatoma cells." (PMID 36268276, 2022). "14% of hepatocellular carcinoma samples had strong ATAD3A expression, whereas percentages of moderate and no ATAD3A expression were 21% and 65%, respectively." (PMID 33280610, 2020).
lung adenocarcinoma (7 papers, 2020 to 2023). A carcinoma that arises from the lung and is characterized by the presence of malignant glandular epithelial cells. "Although ATAD3a is reported to act as an antiapoptotic factor in lung adenocarcinoma and prostate cancer, the detailed underlying mechanism is not known." (PMID 34413925, 2021). "ATAD3A has been shown to positively regulate chemotherapy drug resistance in prostate cancer, lung adenocarcinoma, glioblastoma multiforme (GBM), and uterine cervical cancer." (PMID 37569886, 2023). "Interestingly, in HCC and lung adenocarcinoma, high expression of ATAD3A was correlated with severity of disease, poor prognosis, and low survival rates." (PMID 37569886, 2023). "However, there are few studies on ATAD3A in lung adenocarcinoma, the clinical significance of targeting ATAD3A in the treatment of GLAD deserves further exploration and demonstration." (PMID 33000861, 2020). "High expression of ATAD3A was detected in lung adenocarcinoma (LADC), and overexpression of ATAD3A was also detected in cervical cancer patients." (PMID 38018291, 2023).
prostate carcinoma (6 papers, 2019 to 2023). A carcinoma that arises from epithelial cells of the prostate gland. "ATAD3A expression levels were significantly higher in prostate cancer tissues than in normal prostate cells or benign hypertrophy prostate epithelial cells." (PMID 38018291, 2023). "The high expression of ATAD3A can promote the proliferation of glioma cells and is closely related to the growth of prostate cancer cells." (PMID 38018291, 2023). "In the case of prostate cancer, increased ATAD3A correlates with tumor grade, disease status, lymphovascular infiltration, serum PSA levels, as well as expression of the androgen receptor (AR)." (PMID 33113782, 2020). "Higher expression of ATAD3A is associated with cisplatin resistance and PSA level in prostate cancer." (PMID 31248089, 2019). "Silencing ATAD3A in human prostate cancer cells (LNCaP) significantly reduces cisplatin resistance." (PMID 38018291, 2023). "ATAD3A can be recognized as an anti‐apoptotic factor in prostate cancer." (PMID 38018291, 2023).
glioma (5 papers, 2020 to 2023). A benign or malignant brain and spinal cord tumor that arises from glial cells (astrocytes, oligodendrocytes, ependymal cells). "Overexpression of ATAD3A is also associated with increased cell proliferation in glioma." (PMID 33113782, 2020). "On the other hand, the elevated expression of GNS and ATAD3A/B is associated with poor survival rates in liver cancer, while high expression of GNS in glioma and ovarian cancer is a marker of poor prognosis." (PMID 37775701, 2023). "The WAK358A mutant is the WA dead mutant of ATAD3A and when it is expressed, it becomes incapable of ATP binding, leading to fragmentation of the mitochondrial network in human glioma U373 cells and mouse NIH 3 T3 cells." (PMID 35093151, 2022).
hypertrophic cardiomyopathy (5 papers, 2017 to 2023). A condition in which the myocardium is hypertrophied without an obvious cause. "This study further reiterates the clinical findings associated with ATAD3A pathogenic variation, including developmental delay, hypotonia, congenital cataracts, hypertrophic cardiomyopathy, and cerebellar atrophy." (PMID 33845882, 2021). "Affected individuals exhibited findings previously associated with ATAD3A pathogenic variation, including developmental delay, hypotonia, congenital cataracts, hypertrophic cardiomyopathy, and cerebellar atrophy." (PMID 33845882, 2021). "At least hypertrophic cardiomyopathy has been reported previously in 2 of 8 unrelated individuals carrying the variant c.1582C>T in ATAD3A." (PMID 32021804, 2020). "Finally, two families with other combinations of biallelic variants (non-frameshift indels or missense variants, families 7–8) presented with ATAD3A-associated features such as cataracts and hypertrophic cardiomyopathy." (PMID 33845882, 2021). "Hypertrophic cardiomyopathy has been also reported in one of 6 patients carrying deletions of the ATAD3A and ATAD3B gene respectively." (PMID 32021804, 2020). "We do not agree with the notion that hypertrophic cardiomyopathy and hepatomegaly “expand the phenotypic spectrum commonly associated with pathogenic ATAD3A variants”." (PMID 32021804, 2020).
cervical cancer (4 papers, 2018 to 2023). A primary or metastatic malignant neoplasm involving the cervix. "Some scholars have found that the expression of ATAD3A is significantly correlated with the content of high‐risk human papillomavirus (hrHPV), disease stage, lymph node involvement, and patient survival rate in cervical cancer." (PMID 38018291, 2023). "Moreover, the expression of the anti-autophagy protein ATAD3A in cervical cancer specimens is positively associated with persistent HPV infection, FIGO stage, lymph node involvement, proinflammatory and metastasis-related cytokines, and patient survival." (PMID 29914057, 2018). "In addition, ATAD3A silencing increases autophagosomes number and markedly decreases drug resistance in uterine cervical cancer cells, further underlying the importance of autophagy in HPV-mediated cancer development." (PMID 29914057, 2018). "ATAD3A is increased in HPV-induced cervical cancer, and this study shows that RSV has the potential to counteract HPV-driven processes." (PMID 36558430, 2022). "Treatment of several cervical cancer cells (SKG-I, SKG-II, SKG-IIIa, Nuz & HeLa) with RSV (10, 30 & 100 μΜ) resulted in reduced survival that was associated with a reduction in the anti-autophagy factor ATPase family AAA domain containing 3A (ATAD3A) expression." (PMID 36558430, 2022).
developmental delay (4 papers, 2017 to 2023). "ATAD3A mutations can easily cause embryonic development defects and individual developmental delay." (PMID 38018291, 2023).
Harel-Yoon syndrome (4 papers, 2022 to 2024). A syndromic neurodevelopmental disorder characterized by delayed psychomotor development, intellectual disability, truncal hypotonia, spasticity, and peripheral neuropathy. "Recent expansion of the ATAD3A allelic series demonstrates some individuals with Harel-Yoon syndrome due to dominant negative ATAD3A variants exhibit autoinflammation/autoimmunity and elevated type 1 interferon activity." (PMID 38244259, 2024). "Pathogenic variants in the ATAD3A gene lead to a heterogenous clinical picture and severity ranging from recessive neonatal-lethal pontocerebellar hypoplasia through milder dominant Harel-Yoon syndrome up to, again, neonatal-lethal but dominant cardiomyopathy." (PMID 37095554, 2023). "Loss of ATAD3A in Harel-Yoon syndrome results in autoinflammation due to cytosolic mtDNA leakage." (PMID 38244259, 2024). "Referring to the following databases: Berry DB, DECIPHER, OMIM, and DGV, 1p36.33 contains multiple functional genes such as SKI, GNB1, DVL1 and ATAD3A, among which ATAD3A gene is related to Harel-Yoon syndrome, and the possible clinical phenotypes include psychomotor retardation, mental retardation." (PMID 36471261, 2022).
Huntington disease (4 papers, 2021 to 2024). Huntington disease (HD) is a rare neurodegenerative disorder of the central nervous system characterized by unwanted choreatic movements, behavioral and psychiatric disturbances and dementia. "Acetylation of ATAD3A has been identified to be associated with Huntington's disease, highlighting the significant role of post‐translational modifications in ATAD3A functions." (PMID 39520088, 2024). "Recent findings reveal that ATAD3A is the key protein behind Huntington's disease and Alzheimer's disease, indicative of a potential link between ATAD3A and aging." (PMID 39520088, 2024). "It has been shown that ATAD3A can interact with DRP1 in Huntington’s disease model, and the disturbance of their interaction inhibits mitochondrial fragmentation and mtDNA damage." (PMID 38274803, 2023). "ATAD3A, a MAM protein, interacts with Drp1 in striatal neurons derived from Huntington’s disease (HD) patient-iPSC cells." (PMID 33525374, 2021).
glioblastoma multiforme (3 papers, 2019 to 2023). "In addition, in vitro models of glioblastoma showed that mitochondrial enzyme ATAD3A plays a role in ATM function as silencing of ATAD3A was associated with attenuation of DSB repairs and enhanced radiosensitivity." (PMID 33069104, 2021). "ATAD3A expression correlates with the response to chemoradiotherapy in primary glioblastoma multiforme." (PMID 31248089, 2019).